MYD88 (MYD88 innate immune signal transduction adaptor)
Diseases named in the same sentence as MYD88 in open-access papers (continued):
Sharing a sentence is not in itself a finding about the gene and the disease.
colitis (continued). "GO analysis showed that MyD88 suppression in acute DSS-induced colitis was related to the defense response, immune response and response to organism/external biotic stimulus." (PMID 38946731, 2024). "To investigate the involvement of MyD88 in the pathogenesis of acute colitis, we utilized MyD88-deficient mice in a DSS-induced colitis model." (PMID 38946731, 2024). "Probiotic Clostridium butyricum promotes IL‐10 production by CD11b+CD11c(int) intermediate F4/80+ intestinal macrophages via the TLR2/MyD88 signaling pathway in dextran sodium sulfate (DSS)‐induced colitis." (PMID 38604998, 2024). "The results showed that the protein levels of p65, pp65, p38, phospho-p38 (pp38) MAPK, and MYD88 were upregulated in E. coli-induced mouse colitis compared to the blank control, indicating that E. coli activates both MAPK and NF-κB signaling pathways." (PMID 39765873, 2024). "We next analyzed the possible reasons for the comparable colitis severity between MyD88-suppressed mice and their control animals after DSS challenge." (PMID 38946731, 2024). "This implies that the inhibition of MyD88 and the dysbiosis related to hypo-expression of MyD88 can induce the activation of the NLR signaling pathway in acute DSS-induced colitis." (PMID 38946731, 2024). "The potential for symptom reduction in colitis is suggested by the upregulation of M2 polarization in colitis tissues through the inhibition of MYD88 and ERK signaling pathways." (PMID 39668979, 2024). "Another study showed that L. plantarum AR113 alleviated dextran sulfate sodium (DSS)–induced colitis in mice by downregulating the TLR4/MyD88/NF-κB pathway in the colon." (PMID 37639209, 2024). "To explore the signaling pathways possibly mediating the unmitigated colitis in DSS-fed mice after MyD88 suppression, we performed RNA transcriptome analysis of colon tissue from the DSS + TJ5 mice versus the DSS + PBS mice." (PMID 38946731, 2024). "IN regulated the TLR/MyD88/NF-κB pathway and restored the intestinal microbiota to treat experimental colitis." (PMID 39475104, 2024). "rTsgal also alleviated DSS-induced murine colitis by inhibiting the TLR-4 (TLR-2)/MyD88/NF-κB signaling pathway, reducing excessive inflammatory responses, improving inflammatory cell infiltration and tissue damage." (PMID 39456703, 2024). "For instance, curcumin or melatonin have been shown to inhibit NLRP3 inflammasome and TLR4/MyD88/NF-κB signaling pathway respectively, reducing abdominal pain as well as acting like immune checkpoints in preclinical models of colitis." (PMID 37233492, 2023). "Both oral administration of ALA and fecal microbiota transplantation (FMT) decreased the expression of pro-inflammatory cytokines and restrained the MyD88/NF-κB pathway, which mitigated colitis and ultimately improved host survival." (PMID 38087373, 2023). "Our previous work clearly demonstrates blockade of MyD88 signaling with our novel Myd88 inhibitor, TJ-M2010-5, profoundly relieves colitis and tumor growth in the AOM/DSS-induced CAC mouse model." (PMID 38110638, 2023). "TLR2 stimulation had a protective effect on tight junctions in animals, explants and primary human intestinal cells in culture, and both Tlr2 and Myd88 knockout mice exhibit an accelerated disruption of the barrier following colitis induction." (PMID 37997696, 2023). "We provide the first evidence that ALA can alleviate T. gondii-induced colitis by improving the dysregulation of the host gut microbiota and suppressing the production of pro-inflammatory cytokines via the MyD88/NF-κB pathway." (PMID 38087373, 2023). "We identified a metabolite, ALA, that effectively alleviated T. gondii-induced lethal colitis and showed that its therapeutic effect was mediated by inhibiting the secretion of pro-inflammation cytokines through the inhibition of the MyD88/NF-κB pathway." (PMID 38087373, 2023).
colitis (continued). "Another study also showed that dietary supplementation with 1% Ile reduces the inflammatory response in mice with colitis by downregulating inflammation-related cytokine expression through the TLR4/MyD88/NF-κB pathway." (PMID 36838201, 2023). "Collectively, MyD88 inhibitor-mediated microbial community alternative played a key role in alleviation of colitis, and further protected CAC carcinogenesis." (PMID 38110638, 2023). "Myeloid differentiation factor 88 (MyD88) is an adaptor protein (AP) that is used by most TLRs and MyD88-deficent mice demonstrate defective T cell function and aggravated colitis." (PMID 37191444, 2023). "In this study, the results from Western blot assays suggested that higher levels of TLR4, NF-κB p65, IKB-α and MyD88 were detected in the DSS-induced colitis compared to the control group." (PMID 37761139, 2023). "It has been well established that TLR4 and the downstream binding protein of MyD88 facilitate DSS-induced colitis by activating NF-kB to promote the transcription of inflammation genes." (PMID 37761139, 2023). "Another LGG-secreted protein HM0539 was recently identified as an active factor effectively reducing colitis in rats via activating TLR4/MyD88/NF-кB pathway in enteric cells." (PMID 36918929, 2023). "In comparison with TNBS + PBS group, in the SBP group (5.9 g/kg), the TNBS-induced colitis rats were treated by downregulating the expression levels of MyD88 and NF-κB (p < 0.05)." (PMID 35571126, 2022). "MyD88 signaling has been demonstrated to contribute to necroptosis in spinal cord injury, colitis and acute pancreatitis." (PMID 36213280, 2022). "In conventionally housed IL-37tg mice with DSS induction, IL-37 receptors Il-18r1 and Il1rapl1 mRNA levels and additional downstream signaling pathway genes (Jun, Myd88, Sigirr, Smad3, Stat1, and Stat3) were expressed similarly as in control WT colitis mice." (PMID 35836813, 2022). "In these germ-free animals, KO of TLR/MyD88 alleviates colitis and slows tumor development, indicating that the TLR/MyD88 system is associated with both microbe-dependent and independent processes in inducing inflammation-associated tumorigenesis." (PMID 35625485, 2022). "In DSS colitis model, Clostridium butyricum directly triggers TLR2/MyD88-dependent IL-10 production by intestinal macrophages in inflamed mucosa to prevent colitis development, and this prevention can be negated in macrophage-specific IL-10-deficient mice." (PMID 35967333, 2022). "In the present study, the levels of IL-6, IL-17A, IL-1β, and TNF-α were increased, accompanied by increased expression of TLR5/MyD88/NF-κB pathway in TNBS induced colitis rats." (PMID 35571126, 2022). "We previously showed that MyD88 signaling blockade with MyD88 inhibitor treatment in mice with AOM/DSS-induced CAC leads to reduced incidence of colitis and complete suppression of CAC development." (PMID 35089465, 2022). "In this study, we further investigate the relationship between the destruction of the MUC2-related mucus barrier and the colonic inflammation triggered by the TLR5/MyD88/NF-κB pathway in the TNBS-induced colitis model." (PMID 35571126, 2022). "A deficiency of MyD88 has been shown to cause increased susceptibility to chemically induced colitis and infectious colitis, with IEC-Myd88-/- mice displaying exaggerated tissue damage, reduced antimicrobial responses, and impaired goblet cell responses." (PMID 33557139, 2021). "Ultimately, Cel/PT-LbL Lipo significantly mitigated colitis symptoms and accelerated colitis repair in DSS-treated mice by regulating the levels of pro-inflammatory factors related to the TLR4/MyD88/NF-κB signaling pathway." (PMID 34959287, 2021). "The activation of the TLRs/MyD88 signaling pathway in colitis has been reported to lead to the secretion of large amounts of cytokines by macrophages." (PMID 34567209, 2021).
colitis (continued). "A recent study showed that Tlr4-, Tlr2-, or Myd88-knockout mice exposed to dextran sulfate sodium (DSS) show more severe colitis than wildtype mice." (PMID 34075172, 2021). "The colitis induced up-regulation of M genes related to differentiation of M cells and this is attenuated when MyD88 is knocked out." (PMID 35051090, 2021). "After curcumin treatment, the protein levels of TLR2, TLR4, MyD88, NF-κBp65, p38MAPK, and AP-1 in the colonic tissues of colitis mice were significantly reduced." (PMID 34567209, 2021). "Here, we highlight the crosstalk between the inflammatory response and M cell differentiation and demonstrate that MyD88 was required for colitis- and RANKL-induced up-regulation of genes related to M cell differentiation." (PMID 35051090, 2021). "The results showed that oral Q7-EVs down-regulated TLR4 and MyD88 gene expression compared with DSS-induced colitis mice." (PMID 34925349, 2021). "Clostridium butyricum, another Clostridium strain, which has been clinically used in regulating intestinal health with the mechanism via activating TLR2/MyD88 signaling pathway in colitis." (PMID 34917080, 2021). "The significance of TLR/MyD88 signaling pathway for the recovery of IECs was also shown during acute colitis induced by Helicobacter hepaticus or Citrobacter rodentium." (PMID 34124086, 2021). "The modulating role has also been demonstrated for black tea extract, which reduces physiological manifestations of colitis, regulates the TLR4/MyD88/NF-κB pathway, and causes a selective modulation of the microbiota in chemical-induced colitis in mice." (PMID 34200833, 2021). "This study showed that expression of TLR2, TLR4, TLR9, and MyD88 mRNA was significantly increased in colonic tissues of DSS-induced colitis mice relative to the normal control mice." (PMID 33193406, 2020). "The vital role of MyD88 was shown in experimental models of colitis and experimental autoimmune encephalitis (EAE)." (PMID 32547564, 2020). "Specifically, in mice with MyD88-deficient TECs, the frequency and functionality of thymic CD25+Foxp3+ Tregs was decreased and unable to prevent T cell induced colitis." (PMID 32398640, 2020). "Protein expression of both TLR4 and MyD88 was significantly elevated in colonic tissues of DSS-induced colitis mice compared to the normal control mice by Western blotting." (PMID 33193406, 2020). "Consistently, the cellularity of CD14+moDC is diminished in mice with MyD88-deficient TECs, in which the frequency and functionality of thymic CD25+Foxp3+ Tregs are decreased, leading to aggravated mouse experimental colitis." (PMID 32398640, 2020). "The TLR2/4/MyD88/NF-κB signaling pathway was significantly activated in the DSS-induced colitis group." (PMID 32337275, 2020). "The expression of both TLR4 and MyD88 was significantly down-regulated in HnAb treated colitis mice relative to vehicle-treated DSS-induced colitis mice." (PMID 33193406, 2020). "Collectively, these results suggested that TLR4/MyD88/NF-κB signaling is involved in DSS-induced development of murine colitis, and that HM0539 plays a suppressive role in the DSS-induced inflammatory response." (PMID 33123130, 2020). "Defective MyD88-signalling specifically in IECs reduced host survival in the Helicobacter hepaticus-induced model of colitis, suggesting a key role of TLR-sensing by IECs for barrier restoration." (PMID 31699962, 2019). "In a rat model of TNBS-colitis, curcumin treatment significantly reduced protein expression of MyD88 and NF-κB, prevented the degradation of IκB, and also alleviated symptoms of colitis via a reduction in p38 MAPK." (PMID 31003422, 2019). "This contradicts previous reports on curcumin’s anti-inflammatory effects in colitis, which had been linked to the attenuation of the TLR4/MyD88/NF-κB inflammatory pathway by inhibiting TLR4 homodimerization and decreasing MyD88 expression." (PMID 31026259, 2019).
colitis (continued). "Similar to what was observed in DSS-induced colitis, fewer goblet cells were observed in the colon sections from TNBS-administered WT and MyD88-deficient mice compared to sham controls; moreover, more of the goblet cells were hypotrophic." (PMID 28404987, 2017). "MyD88 deletion inhibited colitis development in a model of spontaneous colitis (SHP-2 IEC-KO mice), rescued the goblet/intermediate cell ratio and prevented NFκB hyperactivation and inflammation." (PMID 28880224, 2017). "In this study, we showed that baicalein significantly inhibited the up-regulation of TLR4 and MyD88 in TNBS-induced colitis mice and in LPS-induced macrophages." (PMID 29180692, 2017). "Although MyD88-mediated pathways are in general considered to be proinflammatory, several studies have also found a critical role for MyD88 in protecting from colitis by promoting intestinal homeostasis." (PMID 28520792, 2017). "Under conditions of injury, however, MyD88-, TLR2-, and TLR4-deficient mice show increased susceptibility to dextran sodium sulfate (DSS)-induced colitis." (PMID 29354132, 2017). "This paradigm shift was supported by Medzhitov and colleagues, demonstrating that microbiota-derived signals via the toll-like receptor (TLR)-related adaptor protein MyD88 protect mice from the development of colitis and intestinal tumor formation." (PMID 29354132, 2017). "Taken together, miR-146a−/− mice appear to be protected from DSS colitis through a mechanism involving enhanced TLR/MyD88 and IFN/Stat1 signaling." (PMID 26456940, 2015). "The MyD88-signaling pathway was shown to be required for monocyte recruitment in DSS-induced colitis." (PMID 24907348, 2014). "Our data show that co-infection with helminth parasite results in the development of exacerbated C. rodentium-induced intestinal inflammation and tissue injury and fatal colitis in mice that lost MyD88-dependent signaling pathway." (PMID 25010669, 2014). "TLR4 and MyD88 KO mice both develop more severe colitis induced by DSS compared to wildtype (WT) controls, with increased bacterial translocation, shown by the greater positivity of mesenteric lymph node cultures for E. coli and Pseudomonas fluorescence." (PMID 24062746, 2013). "Of note, IL-18 uses MyD88 as a downstream signal transduction effector and MyD88 signaling has been shown to have a protective role in the development of AOM/DSS colitis." (PMID 23606794, 2013). "Bovine and mouse infections have shown that the SPI-2 T3SS is necessary for enteric infection and triggers colitis in a MyD88-dependent manner." (PMID 21738750, 2011). "Antibiotic treatment worsened DSS-induced colitis in MyD88−/− mice and prevented epithelial repair, indicating general TLR signaling is required for proper IEC renewal." (PMID 20885960, 2010). "Altogether, these findings indicate that bacterial-induced inflammation promotes the development of colitis-associated colorectal cancer and is dependent on TLR/MyD88 pathway signaling." (PMID 19551144, 2009). "We recently demonstrated that TLR/MyD88 signalling to the NF-κB transcriptional system is critical for commensal bacteria-induced colitis in IL-10−/− mice." (PMID 19841748, 2009). "Recently, it was shown that the induction of colitis in IL-2−/−-mice seems to be toll-like-receptor (TLR) independent, as IL-2−/− MyD88−/− TRIF−/− triple-deficient mice still developed colitis." (PMID 18545662, 2008). "In this study, mice with DSS-induced colitis exhibited significant activation of the TLR4/MyD88/NF-κB pathway alongside the suppression of Nrf2 nuclear translocation and HO-1 expression, indicative of a self-perpetuating cycle of inflammation and oxidative stress that aggravates colonic injury." (PMID 40808691, 2025). "Xia’s research on Lacticplantibacillus plantarum for alleviating colitis found that this probiotic inhibits the expression of MyD88 and NF-kB/p65 signaling pathways and reduces pro-inflammatory factor TNF-α levels, which is consistent with the findings of this study." (PMID 40005605, 2025).
colitis (continued). "This indicates that DSS‐induced colitis activates the TLR4/MyD88/NF‐κB signaling cascade." (PMID 40994452, 2025). "This demonstrates that 4-PBA can regulate TLR4/MyD88/NF-κB-mediated E. coli-induced colitis." (PMID 40076603, 2025). "Furthermore, DM intervention markedly reduced TLR4/MyD88 protein abundance and NF‐κB phosphorylation (p < 0.05), confirming DM's inhibitory effect on TLR4/MyD88/NF‐κB pathway activation in DSS‐induced colitis." (PMID 40994452, 2025). "Our results show that quinic acid could improve the dysbiosis of gut microbiota, alleviate the pathological symptoms of DSS-induced colitis, and inhibit intestinal inflammation by suppressing the activation of the MyD88/NF-κB signaling pathway in mice colon." (PMID 40647020, 2025). "TLR4, MyD88, and NF-κB are key genes in the TLR4/NF-κB pathway associated with colitis." (PMID 40862149, 2025). "In experimental models of colitis, Akkermansia muciniphila has been shown to reduce peritonitis and improve intestinal tissue wound healing after a colonic transmural defect through a MyD88-dependent mechanism." (PMID 39967592, 2025). "Collectively, our findings suggest that muscone may alleviate DSS-induced colitis through the MyD88/p38 MAPK signalling pathway." (PMID 40452925, 2025). "Overall, this research shows that B. animalis may maintain intestinal barrier function, regulate inflammatory cytokines, prevent colitis caused by DSS in mice, block TLR4/MYD88/NF-κB activation, and modify the particular gut microbiota." (PMID 39323474, 2024). "Therefore, we investigated inflammatory responses induced by HY7718 in the colitis mouse model by examining the TLR/MyD88/NF-κB signaling pathway." (PMID 38203747, 2024). "Furthermore, in the IL10−/− mouse model of chronic intestinal inflammation, the deletion of MyD88 protected IL10−/− mice from spontaneous commensal-dependent colitis." (PMID 38946731, 2024). "Another study illustrated that baicalein could alleviate colitis symptoms by inhibiting the TLR4/MyD88 signaling cascade and activating the NLRP3 in mice." (PMID 39421730, 2024). "We hypothesized that the MyD88 inhibition-associated increase in Proteobacteria in the gut might upregulate the NLR signaling pathway, potentially leading to unmitigated colitis severity following MyD88 inhibition." (PMID 38946731, 2024). "Meanwhile, 16S rDNA sequencing and RNA transcriptome analysis revealed a higher abundance of intestinal Proteobacteria and an up-regulation of the nucleotide oligomerization domain-like receptors (NLRs) signaling pathway in colitis mice following MyD88 suppression." (PMID 38946731, 2024). "Meanwhile, inhibition of MyD88 can effectively slow the progression of colitis to colon cancer." (PMID 38785969, 2024). "Treg-specific Myd88 deletion mice showed deficiency in the intestinal Treg cells, increased numbers of TH17 cells, and enhanced IL-17-dependent inflammation in experimental colitis." (PMID 37191444, 2023). "Thus, blocking MyD88 signaling markedly influenced the composition of gut microbiome that contributed to alleviating colitis and tumor burden in the murine model of CAC." (PMID 38110638, 2023). "There have been many reports suggesting that polysaccharides from natural plants are beneficial to intestinal health; for example, ginseng polysaccharides can improve TLR4/MyD88/NF-κB-induced colitis by inhibiting the activation of dextran sulfate sodium (DSS)." (PMID 37415978, 2023). "Therefore, inhibiting the TLR4/MyD88/NF-κB signaling pathway is an attractive approach for the therapy of colitis." (PMID 36193153, 2022). "In contrast, another study reported MT’s positive outcomes in TNBS (trinitrobenzene sulfonic acid)—induced colitis in mice are mediated by the inhibition of inflammation through the down-regulation of the TLR4/Myeloid differentiation primary response 88 (MyD88)/NF-κB pathway." (PMID 36421432, 2022).